ESR1 (estrogen receptor 1)
Diseases named in the same sentence as ESR1 in open-access papers (continued):
Sharing a sentence is not in itself a finding about the gene and the disease.
tumor (continued). "Thus, tumor formation seems to depend on intramammary levels of both reactive estrogen biotransformation products and free estrogens able to activate ESR1." (PMID 34921608, 2022). "Thus, HSA may possibly modulate E2 and ESR1 and hinder this signaling pathway to suppress tumours growth." (PMID 35386216, 2022). "Indeed, AR and ESR1 were identified as the targets of the sex hormones testosterone and estradiol, respectively, whereas HDACs and BRDs were suppressed upon treatment with the anti-tumor drugs vorinostat and JQ1." (PMID 35073843, 2022). "In the tumor tissue, the mutational analysis revealed a p.(Hys1047Leu) PIK3CA mutation at 36.9% frequency, and the ctDNA NGS analysis validated the tissue mutation but also identified a second mutation in the ESR1 gene (p.(Asp538Gly), 0.39%), usually associated with endocrine resistance." (PMID 35682999, 2022). "Overall, E2 levels were significantly positively correlated with tumor enrichment in the hallmark estrogen response pathway (red bars) and with the expression of genes demonstrated to be transcriptionally regulated by ER (BCL2, IGF1R, GATA3, PIK3CA) and ligand-dependent ER (ESR1, XBP1, TFF1)." (PMID 36428742, 2022). "Although the HCI-013 PDX model was originally developed in mice with exogenous E2 supplementation, we hypothesized that the presence of the Y537S mutation in ESR1 might render the tumor independent of estrogen." (PMID 34717714, 2021). "The successful validation of the variants in tumor DNA for 18 of 18 mutations and not present in 11 of 11 matched germline DNA confirms that our RNA-seq–based approach is specific for detection of true-positive somatic ESR1 mutations." (PMID 33937624, 2021). "Moreover, higher pCR in patients with elevated expression of ERBB2, KRT20 or ESR1 may support previous studies showing a lower cancer-specific and relapse-free survival of MIBC patients with high ESR1-expressing tumours." (PMID 34073233, 2021). "Moreover, 40–85% of BC patients presented hypermethylation of the ESR1 gene that highly correlated with ER-negative/progesterone receptor (PR) negative conditions, suggesting that ESR1 methylation status strongly contributes to tumor phenotypes." (PMID 34863151, 2021). "Furthermore, we performed in-depth studies to understand the mechanism and illustrated that ESR1 may act as a tumor suppressor by inhibiting the JAK/STAT3 signaling pathway." (PMID 33865377, 2021). "By using Esr1-Cre/MMTV-TVA/Rosa26-tdRFP mice infected with RCAS-Erbb2 (to generate HER2-positive tumors), the authors could demonstrate that ERαpos tumor cells with an overexpression of HER2 have to progressively lose their ERα expression in order to clonally expand and metastasize." (PMID 35052683, 2021). "ESR1 may exert a tumor suppressor function by inhibiting the JAK/STAT3 pathway." (PMID 33865377, 2021). "Thus, Esr1 might protect against tumor development initially but then promote tumor growth in more advanced lesions." (PMID 34068249, 2021). "However, the role of ESR1 or ESR2 had a considerable difference in diverse tumor types." (PMID 32536040, 2020). "However, when we further adjust the tumor stage/grade/status of the patients, only LIHC and MESO showed significant survival association with ESR1 mRNA expression, while BRCA, KICH, KIRP, LGG, and PAAD patients survival significant association with ESR2 mRNA expression." (PMID 32536040, 2020).
tumor (continued). "The ineffectiveness of mTORC1 inhibitors in tumor treatment and in functional reactivation of ESR1 may be related to incomplete inhibition of 4E-BP1 phosphorylation, because rapamycin was known to potently inhibit phosphorylation of S6RP but not that of 4E-BP126,44,59,60." (PMID 30050079, 2018). "Four of the right cases with undetectable ESR1 mutation at progression were also PIK3CA mutated at baseline and all of these had PIK3CA mutation detected at the end of treatment, indicating the observed loss of ESR1 mutation was not an artifact of low tumor content." (PMID 29497091, 2018). "However, our results are limited by the small number of blood draws that were available for patients with ESR1 mutations (range; 1-4), unlike frequent measurements of the tumor marker CA 27.29." (PMID 28978004, 2017). "Thus, there might be an association between low ESR1, PGR and PRLR expression and the associated prognosis of the tumor." (PMID 27649560, 2016). "Decrease of ESR1 in tumors of YA-BC patients as compared to MA-BC patients may cause tumor growth no longer under estrogen control." (PMID 27152840, 2016). "ESR1 mutation was also not found in this patient′s primary tumor test." (PMID 27706044, 2016). "Thus, methylation mediated silencing of ESR1 can lead to spread of a tumor." (PMID 27158284, 2015). "Based on the apparent relevance of ERBB2 and ESR1 mRNA levels in discriminating patients with low or high risk of relapse, we applied to our dataset the PAM50 subtype predictor, which identifies the HER2-enriched (HER2E) subtype as the tumor group most responsive to trastuzumab." (PMID 26334217, 2015). "Via IPA, ESR1 and NFkB were linked to developmental disorder, reproductive system disease, cellular growth and proliferation; MYC was linked to cancer, infection mechanism, gene expression and tumor morphology; and ERK1/2 was linked to molecular transport, protein trafficking and cell cycle." (PMID 22616791, 2012). "On the other hand, the stage (p = 0.0003), tumour size (p = 0.0029), histological grade SBR (p = 0.0011), lymph node status (p = 0.0288), oestrogen receptor status (p = 0.0054), metastasis (p < 0.0001) and death (p = 0.0105) were significantly associated with ESR1 gene methylation." (PMID 20109227, 2010). "When the expression of genes affecting the metastasis or suppression of tumor cells was investigated, urotensin-II increased MTA-1 and ESR1 expression and decreased Kiss1 expression." (PMID 42287353, 2026). "The data revealed that the expression of Smyd3 and Esr1 at the mRNA level was increased in MTV, MTP12, and tumor tissues compared with age-matched Brca1-WT controls." (PMID 40157910, 2025). "In obese EA patients, enriched pathways were dominated by extra-nuclear estrogen signaling (e.g., ESR1, ESR2, HEY2, MCL1), suggesting a strong hormonal component in TNBC tumor biology." (PMID 41009685, 2025). "Especially, ESR1 gene expression was significantly inhibited by DNA methylation in OCCC, while cellular iron retention signaling was much enhanced in this tumor type." (PMID 40076621, 2025). "The RT-qPCR analysis revealed significantly decreased expression of ESR1, APOA1, IGF1, PPARGC1A, SERPINE1 and PON1 in tumor tissues compared with adjacent normal tissues (P < 0.05)." (PMID 40317014, 2025). "By activating downstream pathways, such as the p38 MAPK pathway, ESR1 helps limit the migration and invasion of HCC cells, which are critical factors in tumor metastasis." (PMID 40317014, 2025). "Instead, ESR1-rearranged UTROSCT occurred at a mean age of 39.9 years, appearing as a tumor that preferentially affected premenopausal women." (PMID 40150134, 2025). "Using systems pharmacology, we identified 50 anti‐HCC core targets, including EGFR, c‐Myc, ERBB2, ESR1, CCND1, and HSP90AA1, all of which play critical roles in tumor initiation, proliferation, angiogenesis, and resistance mechanisms." (PMID 40727254, 2025).
tumor (continued). "In PC, the genes ESR1 and SRC exhibited overexpression in tumor tissues, whereas IL1B and CTNNB1 showed reduced expression." (PMID 41186627, 2025). "Whereas both ESR1 and ESR2 display considerable sequence homology, they exert diverse actions in tumor initiation and development." (PMID 40243758, 2025). "The combined assessment of circulating tumor cell (CTC) and ESR1 status in liquid biopsy samples has been highlighted for its potential to enhance the predictive clinical value in metastatic BC." (PMID 40732251, 2025). "To further validate these findings, we conducted qPCR analysis to assess the expression of ESR1, BRCA1, CTNNB1, and BAX in tumor tissue." (PMID 39045563, 2024). "Although the study suggests encouraging anti-tumor effects of gomisin B in MYCN-amplified NB cells, further exploration is required to understand its actual mechanism in regulating ESR1 and its interactions with chemotherapy drugs." (PMID 38313313, 2024). "These gene fusions, such as GREB1::NCOA2 and ESR1::NCOA2, result in the aberrant activation of estrogen signaling pathways, driving the proliferation and survival of tumor cells." (PMID 38276058, 2024). "The mRNA expression of RXRα, AKT1, ESR1, MAPK1, and HSP90AA1 was analyzed in different tumor tissues." (PMID 38835342, 2024). "Additionally, ESR1, OTUD6B, USP2, and USP37 showed a positive correlation with risk scores, while USP22 exhibited a significant negative correlation with risk scores (r = -0.7, p < 0.0001), suggesting a potential role for these genes in ESCC tumor progression and patient prognosis." (PMID 39742278, 2024). "The mRNA expression of RXRα, AKT1, ESR1, MAPK1, and HSP90AA1 in tumor and normal tissues was analyzed using the GEPIA database." (PMID 38835342, 2024). "Only patients with high expression of ESR1 and BUB1 in tumor tissue showed a worse prognosis in terms of overall survival (OS) compared to those with low expression." (PMID 38831458, 2024). "In a fourth RNA-Seq data set consisting of 73 samples, expression of ESR1 and PGR was again significantly increased in tumor samples following ADT." (PMID 38625747, 2024). "The correlation between the DNA methylation beta-value and the RNA level of ESR1, ESR2, and GPER1 was analyzed through cBioPortal in 19 tumor types." (PMID 38666956, 2024). "Increased HOTAIR expression induces epigenetic changes on both ESR1 and BRCA1 genes, promoting increased expression of ER-alpha, strengthening DNA stabilization and tumor regression." (PMID 39329990, 2024). "We found that ESR1 gene amplification was specifically selected in patients treated with adjuvant AI- and/or LHRHa-based therapy, thus suggesting that it could be a novel mechanism of tumor resistance to ET in HR+ HER2- BC beyond the more studied and previously characterized ESR1 mutations." (PMID 36595552, 2023). "Many of these tumours display high expression of proliferation and DDR pathway modules compared with cluster 1 and low expression of ESR1/PGR." (PMID 37574209, 2023). "After transfected with ESR1 or ESR2, both the mRNA and protein expression levels of ESR1 or ESR2 in tumor cells were significantly upregulated." (PMID 36765788, 2023). "The results of qRT-PCR and IHC analysis showed that PAFAH1B3, ZIC2, and ESR1 were differentially expressed in HCC and normal tissues and that patients with high TEXSRGs-scores had higher TEX infiltration abundance and tumor stemness gene expression." (PMID 37957420, 2023). "In the cases of invasive BC from the TCGA database in UALCAN, the mRNA levels of AKT1, ESR1, HSP90AA1, CASP3, SRC, and MDM2 were significantly increased in tumor tissues." (PMID 36882618, 2023). "More studies should further investigate the relationship between ESR1 and MMP9 in the pathogenesis of uLMS, but it is possible that these two genes, alone or combined, have an influence on tumor behavior." (PMID 37373974, 2023).
tumor (continued). "The top 3 hub-genes, namely AKT1, ESR1 and HSP90AA1, identified by protein–protein interaction network analysis using Tamarixetin targets, are known to play prominent roles in tumor progression." (PMID 35273218, 2022). "Owing to depriving ESR1 fusion proteins of the LBD, tumor cells undergoing such alterations have been shown to be insensitive to endocrine therapy." (PMID 35764927, 2022). "Among these genes, PLK1, CDC25C, ESCO2, AXIN2, TREX2, ALKBH2, and MC1R were upregulated in tumor tissues, whereas IGF1 and ESR1 presented downregulation." (PMID 35484177, 2022). "Moreover, our study did not analyse the relationship between 18F-FES uptake and ESR1 gene amplification and mutation in the tumour biopsy, as these assays provide insufficient data at present to guide therapy for HR + /HER2- MBC and are not performed routinely in our centre." (PMID 36028895, 2022). "Tumours were considered as luminal type if they had a high expression of ERBB2, ESR1, or KRT20 while showing a low expression of KRT5." (PMID 34073233, 2021). "Through a systems medicine approach, it was determined that hub biomolecules, AR, GATA2, miR-124, TOR1AIP1, ESR1, EGFR, STAT1, miR-192, GATA3, COL1A1, in tumor microenvironment generic network." (PMID 33907495, 2021). "Another in-frame ESR1-e6 fusion, ESR1-e6>NOP2, was detected in a primary tumor but was found to be transcriptionally inactive." (PMID 34711608, 2021). "Together, ESR1, ESR2, and PGR are likely closely correlated and have a role in multiple tumor genesis." (PMID 34322374, 2021). "Formalin-fixed paraffin-embedded tumour tissue samples from TUR-BT of 54 patients (42 males, 12 females, median age of 64) with MIBC were analyzed for KRT20, KRT5, ESR1, and ERBB2 mRNA expression." (PMID 34073233, 2021). "To examine the clinical relevance of ESR1, ESR2, and PGR in pan-cancer, we analyzed the correlations of their expression with tumor stage." (PMID 34322374, 2021). "ER-α (protein product of ESR1) agonist treatment in a mouse model of HCC resulted in significantly longer survival and decreased tumor burden (p<0.0001), with inhibition of Wnt/β-Catenin signaling." (PMID 34881186, 2021). "The concordance rate between ESR1,PR, HER2 expression on EpCAM(+) CTC fractions and the primary tumor was 27.9%, 34.9% and 65.1% respectively." (PMID 33799422, 2021). "The expression levels of AR, CAT, CYP3A4, ESR1 and SLC10A1 were markedly upregulated in primary tumour tissues compared with normal tissues." (PMID 34717619, 2021). "Promising data were reported in a PDX model resistant to tamoxifen and fulvestrant plus palbociclib with ESR1-E380Q and PIK3CA-E545K/E722K, in which tumor growth was inhibited by elacestrant and even more so with elacestrant combined with everolimus." (PMID 34392831, 2021). "Our results indicate that ESR1 promotes SLC7A11 transcription to resistance ferroptosis and cytotoxic stress, thereby promoting tumor malignancy." (PMID 35252218, 2021). "Genetic alterations and immunological effects of ESR1, ESR2, and PGR were analyzed using the cBioPortal and Tumor and Immune System Interaction Database (TISIDB), respectively." (PMID 34322374, 2021). "(ESR1, a well known marker of BRCA, was ranked in the top 1.2% of all genes for BRCA, but ranked much worse for other tumor types)." (PMID 31971940, 2020). "The KEGG enrichment result showed that ESR1 and ESR2 significantly correlated genes were mainly enriched in immune response and tumor‐related cellular signaling pathways in most cancer types." (PMID 32536040, 2020). "The pan‐cancer analysis showed significantly different mRNA expression of ESR1 in nine tumor types and ESR2 in four tumor types." (PMID 32536040, 2020).
tumor (continued). "No studies, to our knowledge, have comprehensively explored evidence for bimodal age distribution at diagnosis across quantitative protein-based (i.e., percent ER-positivity) or RNA-based (i.e., ESR1 and PAM50) tumor characteristics." (PMID 31535320, 2020). "Significant decreased in ESR1 and PGR signal was also detected after 10 days of culture in tumour L6 and L9, respectively." (PMID 32251338, 2020). "ESR1 has been reported to affect tumor cell migration, the relationship among FBXL19-AS1, hsa-miR-22-3p, and ESR1 needs further verification." (PMID 33344260, 2020). "A similar positive correlation between MAGI1, ESR1, and GATA3 expression is also found in tumor samples derived from the MMTV-PyMT spontaneous model of BC." (PMID 31963297, 2020). "The GSs that measure oestrogen signalling (ERTarget27-GS, SET-GS, ESR1.2-GS, ESR1.1-GS) were also significantly less suppressed by AI in HER2+ tumours." (PMID 31892336, 2019). "The RNA expression data from the TCGA_LIHC cohorts revealed that increased ESR1 mRNA expression correlated significantly with gender, age, serum AFP, TNM stage, tumor recurrence and tumor differentiation." (PMID 31410310, 2019). "Conversely, in the ESR1 Y537S mutant PDX model, palbociclib alone or in combination with bazedoxifene similarly inhibited tumor growth, but the combination proved more effective in decreasing Ki67 expression than either agent given as monotherapy." (PMID 31795152, 2019). "First, as a control, we show that as expected oestrogen receptor alpha (ESR1) and progesterone receptor (PGR) were significantly different between these groups, with median expression in ER-negative tumours dramatically lower than in ER-positive tumours." (PMID 31683867, 2019). "In multivariable analysis in the ESR1+/ERBB2- set the MKI67 status and tumor stage displayed almost identical hazard ratios, however only stage was clearly significant." (PMID 31307414, 2019). "High ESR1 expression was associated with lower pCR rates (OR 0.73, 95% CI 0.65–0.82, p < 0.0001) in univariate analysis, even in the subgroup of patients with luminal tumours (OR 0.60, 95% CI 0.40–0.91, p = 0.0149), but not in multivariate analysis (data not shown)." (PMID 31728025, 2019). "ESR1 promoter methylation has been reported as an independent biomarker for aggressive MBC, due to its correlation with high mitotic count and high tumor grade." (PMID 29731982, 2018). "E2 decreased survival time by 61% in mice with wild-type Esr1, and by 38% in mice with Esr1 deleted in the OSE, showing that ESR1 partially mediates E2 tumour promotion in this mouse model." (PMID 29973689, 2018). "These pathways involve ESR1, IGF1R, and pro-death UPR-mediated apoptosis and inflammation with subsequent recruitment of tumor-infiltrating lymphocytes." (PMID 29796176, 2018). "Correlations between ID4 expression and the expression of FOXA1, ESR1, GATA3, CCND1, AKT, and IGF1R in the complete tumor cohort (ER+ and ER−)." (PMID 30139383, 2018). "On the other hand, the observation that two patients harboured ESR1 mutations at relapse confirms the hypothesis that mutational clone emergence was selected by AI therapy during the adjuvant setting, but not detectable at that time given a low tumour burden." (PMID 29769099, 2018).